CST3 (cystatin C)
Diseases named in the same sentence as CST3 in open-access papers (continued):
Sharing a sentence is not in itself a finding about the gene and the disease.
lymphoma (6 papers, 2004 to 2024). A malignant (clonal) proliferation of B- lymphocytes or T- lymphocytes which involves the lymph nodes, bone marrow and/or extranodal sites. "Also, in order to better understand the role of CTSS in the origin and development of lymphoma, its association with cystatin C (Cys C), lipids, and inflammatory markers was analysed." (PMID 39712508, 2024). "Our results show a correlation of cystatin C with IPI in the group of aggressive lymphomas and in the subgroup of aggressive nodal lymphoma." (PMID 24167744, 2013). "At the time of diagnosis, cystatin C showed significant correlation with β2M in total group of patients and in the group of nodal aggressive lymphomas." (PMID 24167744, 2013). "The correlation between cystatin C and clinical stage of disease at the time of diagnosis was significant in the group of aggressive lymphomas and in subgroup with nodal presentation." (PMID 24167744, 2013). "Our results show that cystatin C correlates with β2M in the total group of patients and in the group of aggressive nodal lymphoma." (PMID 24167744, 2013). "In patients who achieved partial or complete remission after three cycles of chemotherapy, the level of cystatin C significantly decreased, in total patient's group and in group with aggressive lymphoma." (PMID 24167744, 2013). "In the group of aggressive lymphomas (N = 34), twenty-one (61,8%) patients had the lower cystatin C level before fourth cycle of therapy." (PMID 24167744, 2013). "Cystatin C levels were significantly elevated in patients with elevated LDH activity compared to those with normal LDH activity in a group of aggressive lymphomas." (PMID 24167744, 2013). "In the mouse lymphosarcoma model, the cystatin C concentrations in the plasma and other tissues reliably reflected the changes in tumour volume following cytotoxic therapy." (PMID 15138478, 2004). "Our results show that cystatin C should be taken into consideration in lymphoma monitoring." (PMID 24167744, 2013). "Then, the cystatin C values of these two groups were compared, for each type of lymphoma." (PMID 24167744, 2013). "Considering the obtained correlations and the fact that the increased levels of β2M indicate the patients with the aggressive lymphomas who will experience relapse, we analyzed correlation between cystatin C and β2M in patients with partial or complete remission after three cycles of chemotherapy." (PMID 24167744, 2013). "However, in some hemoblastoses (lymphoma, lymphogranulomatosis) opposite data were obtained: increased serum cystatin C level was revealed, and – decreased cystatin C concentration in acute leukosis." (PMID 23984285, 2013). "Then, the values of cystatin C of these two groups were compared, for each type of lymphoma." (PMID 24167744, 2013). "However, we expect that the disease-free and overall survival analysis will give the definitive answer about the reliability of cystatin C as an indicator of course of aggressive lymphomas." (PMID 24167744, 2013). "Moreover, cystatin C is produced by all nucleated body cells, so the correlation of the inhibitor level and clinical stage of disease in aggressive nodal lymphomas can be the result of the general response of organism to the increased proteolytic activity in the infiltrated lymph nodes." (PMID 24167744, 2013). "Based on the results of correlation of cystatin C and β2M and on the basis of previous studies indicating the importance of β2M as a prognostic factor in aggressive lymphomas, it may be concluded that cystatin C could serve as an indicator of course and prognosis of the disease." (PMID 24167744, 2013). "In patients with aggressive lymphoma, the group with elevated LDH had significantly higher level of cystatin C than the group with normal LDH activity." (PMID 24167744, 2013). "The correlation between cystatin C and IPI at the time of diagnosis was significant in total group of patients and in the group with nodal aggressive lymphomas." (PMID 24167744, 2013).
lymphoma (continued). "Does this mean that there is a specific mechanism in aggressive lymphomas, not present in patients with indolent lymphoma, which contributes to decreased levels of cystatin C in disease remission?" (PMID 24167744, 2013). "The cystatin C level was significantly increased in total group of patients over 60 years old, while in particular types of lymphoma, no statistical significance has been obtained." (PMID 24167744, 2013). "This is the leading study to analyze the influence of serum cystatin C level—showing sensitivity and specificity—on the disease-free survival and overall survival probability of DLBCL patients; DLBCL denotes the most common subtype of NHL, it is accounting for 30%–40% amongst lymphoma cases." (PMID 28282874, 2017).
ovarian cancer (6 papers, 2013 to 2025). A primary or metastatic malignant neoplasm involving the ovary. "Different studies have shown that the balance between cysteine proteases (such as cathepsin B) and their inhibitor cystatin C is critical in regulating ovarian cancer invasion." (PMID 41149076, 2025). "On the other hand, serum cystatin C levels are elevated in patients with malignant ovarian tumors compared with those with benign tumors and healthy controls." (PMID 41149076, 2025). "While reduced expression of cystatin C was observed in skin during the development of epithelial cancer, an increase in cystatin C expression was reported in ovarian cancer." (PMID 29088746, 2017). "According to the literature, cystatin C, as well as mature cathepsin B, were involved in the mechanism of invasion of ovarian cancer; however, this mechanism was not well understood." (PMID 23986888, 2013). "It was suggested that the serum cystatin C changes in ovarian cancer were minor and unrelated to the diagnosis or prognosis of this tumour." (PMID 23986888, 2013). "Large increases of procathepsin B level (about 13-fold, p<0.001) and to a lesser degree of cystatin C (1.8-fold, p<0.05) and cystatin B levels (1.4 fold, p<0.001) were revealed in ascites fluids of patients with ovarian cancer compared to the control serum." (PMID 23986888, 2013). "A significant difference (p<0.05) between cystatin C level in ascetic fluids of persons with ovarian cancer and a benign tumour can be potentially useful in differential diagnosis of those diseases." (PMID 23986888, 2013). "In addition, higher levels of cystatin C have been detected in the cyst fluid of patients with ovarian cancer and in the sera of patients with lung or colorectal cancer." (PMID 29088746, 2017). "At the same time, one can argue that in the diagnosis or prognosis of ovarian cancer, the study of cystatin C in ascetic fluids might be more important than in serum." (PMID 23986888, 2013). "Cystatin C concentration in ascites fluid increased only in patients with ovarian cancer (p<0.05) and did not change in the benign tumours group." (PMID 23986888, 2013). "According to our results, cystatin C increased only in ascetic fluid (not in serum) of patients with ovarian cancer and did not increase in the benign tumour group." (PMID 23986888, 2013).
Parkinson disease (6 papers, 2015 to 2025). A progressive degenerative disorder of the central nervous system characterized by loss of dopamine producing neurons in the substantia nigra and the presence of Lewy bodies in the substantia nigra and locus coeruleus. "As a personalized marker, a higher cystatin C concentration was shown for some individual patients in the culture medium of midbrain organoids, suggesting a potential involvement in Parkinson's disease physiopathology." (PMID 39958955, 2025).
periodontitis (6 papers, 2017 to 2024). An acute or chronic inflammatory process that affects the tissues that surround and support the teeth. "In addition, increased levels of cystatin C are associated with decreased kidney function, meaning that in the presence of both diseases (periodontitis and CKD), cystatin C was higher, and this can lead to the worst periodontal condition and kidney function." (PMID 35225864, 2022). "In addition, Il-10 gene polymorphisms may be associated with a predisposition to chronic periodontitis development, which indicates cystatin C could contribute to the inflammatory process decrease by IL-10 production." (PMID 38708345, 2024). "Due to the importance of controlling the inflammatory response during the development of periodontitis, in the present study, we investigated the effect of cystatin C on P. gingivalis-infected macrophages." (PMID 38708345, 2024). "In this study, we analyzed the antimicrobial activity of cystatin C against P gingivalis, which contributes to the development of chronic periodontitis." (PMID 36312752, 2022). "The results of our study suggest that NO expression could lead to the gradual progression of periodontitis after proinflammatory cytokine production by HGFs infected by P. gingivalis and that cystatin C protects from tissue damage through the reduction of these free radicals." (PMID 36312752, 2022).
pneumonia (6 papers, 2020 to 2025). An acute, acute and chronic, or chronic inflammation focally or diffusely affecting the lung parenchyma, caused by an infection in one or both of the lungs (by bacteria, viruses, fungi, or mycoplasma.). "As such, cystatin C may be a useful therapeutic target for protection against the consequences of pneumonia caused by P. aeruginosa." (PMID 33030263, 2020). "However, in cases with documented inflammatory conditions (e.g., ANCA vasculitis, pneumonia), we observed a trend toward lower eGFRcysC values, consistent with the known effect of inflammation on cystatin C generation." (PMID 41516239, 2025). "The SI based on serum creatinine and cystatin C can predict pneumonia rather than other postoperative complications among older patients with hip fracture after joint replacement surgery." (PMID 34641805, 2021).
rheumatoid arthritis (6 papers, 2021 to 2023). A chronic, systemic autoimmune disorder characterized by inflammation in the synovial membranes and articular surfaces. "There is evidence that cystatin C is implicated in several inflammatory autoimmune diseases such as rheumatoid arthritis." (PMID 36482996, 2022).
thyroid disorders (6 papers, 2021 to 2025). "At the same time, a study of thyroid-associated orbitopathy revealed cystatin-C (CST4) among the top upregulated proteins, as we observed it for patients with CRVO among numerous defending proteins." (PMID 36498980, 2022). "Additionally, extra-renal conditions such as inflammation, thyroid disorders, and neoplasia can also increase cystatin C concentrations." (PMID 40804960, 2025). "While incorporating cystatin C into eGFR calculations improves accuracy, this has been demonstrated primarily in outpatient settings, and cystatin C is influenced by factors like inflammation, adiposity, thyroid disorders and medications which can affect the reliability of eGFR calculations." (PMID 38730983, 2024). "First, previous studies have found potential associations of cystatin C with thyroid dysfunction, but we did not have data on thyroid-related diagnoses or medications." (PMID 35175342, 2022). "Furthermore, non-renal conditions such as inflammation, thyroid disorders, and neoplasia can also elevate cystatin C concentrations." (PMID 40804960, 2025).
AIDS (5 papers, 2016 to 2024). A syndrome resulting from the acquired deficiency of cellular immunity caused by the human immunodeficiency virus (HIV). "Both cystatin C and galectin-9 have been shown to be associated with various non-AIDS adverse events in persons with chronic HIV during suppressive antiretroviral therapy." (PMID 37569647, 2023). "Hence, we planned a study to assess plasma galectin-9 levels in PLHIV on ART and their associations with plasma viral load, cystatin C levels, and other parameters possibly contributing to non-AIDS events." (PMID 37569647, 2023). "We suspect that, in the present case, the elevated cystatin C reflected the widespread inflammation and T-cell activation associated with multiple opportunistic infections in the setting of a new diagnosis of AIDS, along with the effects of high-dose corticosteroid therapy." (PMID 27293926, 2016). "Cystatin C has been suggested to be a more accurate glomerular filtration rate (GFR) surrogate than creatinine in patients with acquired immunodeficiency syndrome (AIDS) because it is unaffected by skeletal muscle mass and dietary influences." (PMID 27293926, 2016). "There is limited data regarding the use of Cystatin C based eGFR concentration in HIV & AIDS infected individuals on ART." (PMID 38654183, 2024). "In this cross-sectional study, we evaluated the clinical utility of Cystatin C based eGFR in assessing renal function among patients with HIV/AIDS on ART at Mildmay Uganda." (PMID 38654183, 2024). "We report our experience in a treatment-naïve patient with a new diagnosis of acquired immunodeficiency syndrome (AIDS) in whom cystatin C falsely underestimated GFR." (PMID 27293926, 2016). "In this case of a patient with a new diagnosis of AIDS, cystatin C falsely underestimated the patient's renal function." (PMID 27293926, 2016). "We recommend that ART programs could explore Cystatin C based eGFR as a confirmatory test for assessment of renal function in HIV&AIDS patients." (PMID 38654183, 2024). "The correlation of galectin-9 levels with other parameters like cystatin C levels and blood pressure was also analyzed in a subset of aviremic individuals on long-term ART to determine their association with factors contributing to non-AIDS events." (PMID 37569647, 2023). "It is unclear why cystatin C was falsely elevated, but we hypothesize that it relates to the proinflammatory state with AIDS, opportunistic infections, and corticosteroids." (PMID 27293926, 2016). "Cystatin C based eGFR exhibited a high specificity and a high positive likelihood ratio in diagnosis of kidney disease among HIV&AIDS patients." (PMID 38654183, 2024). "The combined effect of galectin-9 and cystatin C on HIV replication impacting HIV viremia and of its contribution to the development of non-AIDS events through inflammaging needs to be explored further." (PMID 37569647, 2023). "Levels of both cystatin C and galectin-9 correlating with duration of ART suggest a need for screening PLHIV on long-term ART for non-AIDS events." (PMID 37569647, 2023). "Cystatin C based eGFR has been proposed as a potential renal function marker but its use in HIV&AIDS patients has not been well evaluated." (PMID 38654183, 2024). "AIDS Clinical Trials Group study A5224 showed the inverse correlation of systemic inflammatory markers and eGFR in HIV patients both before and during ART using the equation CKD-EPI with cystatin C-creatinine (CysC-Cr), suggesting that systemic inflammation may result in renal impairment." (PMID 32762646, 2020).
benign prostatic hyperplasia (5 papers, 2017 to 2025). A non-cancerous nodular enlargement of the prostate gland. "Additionally, the elevated level of cystatin C (HR = 1.60; 95% CI = 1.50–1.70, P < 0.001) and urea (HR = 1.10; 95% CI = 1.10–1.10, P < 0.001) demonstrate a significant positive association with benign prostatic hyperplasia." (PMID 39582249, 2024).
bipolar disorder (5 papers, 2015 to 2025). A disorder of the brain that causes unusual shifts in mood, energy, activity levels and the ability to carry out day-to-day tasks. "It is thought that inflammation significantly contributes to the development of bipolar disorder (BD), and recent findings indicate a connection between cystatin C and immune-related inflammation." (PMID 40256164, 2025). "We report novel causal relationships found by four or more MR methods between glucose and bipolar disorder (Mean Effect Size estimate across methods: 0.39) and between cystatin C and bipolar disorder (Mean Effect Size: -0.31)." (PMID 39000484, 2024). "For the glucose on bipolar disorder the average effect estimate is 0.39 with a range of (0.29, 0.55), while cystatin C has an inverse relationship on bipolar disorder with the average effect size of −0.31 ranging from −0.107 to −1." (PMID 39006413, 2024). "We report novel causal relationships found by 4 or more MR methods between glucose and bipolar disorder (Mean Effect Size estimate across methods: 0.39) and between cystatin C and bipolar disorder (Mean Effect Size: −0.31)." (PMID 39006413, 2024). "Of note, we discovered a strong, direct relationship between glucose and bipolar disorder and a strong, inverse relationship between cystatin C levels and bipolar disorder which, to the best of our knowledge, has never been directly reported before." (PMID 39006413, 2024). "We also found associations between rare PTV/missense variants in C17orf78 with elevated cystatin C (ß=0.51, 95% CI 0.23 to 0.80, p=3×10−4) and SYNRG with increased risk of bipolar disorder (OR=27.45, 95% CI 3.03 to 248.61, p=8×10−4)." (PMID 36109160, 2023). "Additionally, our analysis also discovered two relationships of note: a direct relationship between glucose and bipolar disorder and an inverse relationship between cystatin C and bipolar disorder." (PMID 39006413, 2024). "A common treatment for bipolar disorder is lithium, which has been shown to decrease renal function and can lead to elevated cystatin C levels, which may lend further insight to the mechanism behind lithium’s use as a treatment, however this remains to be confirmed." (PMID 39006413, 2024).
glomerular disease (5 papers, 2018 to 2025). "Numerous studies of cystatins in dogs have been reported, however, only serum cystatin C is evaluated as a biomarker in dog’s glomerular disease." (PMID 30513116, 2018). "The term SPS is based on the pore model of glomerular disease, which proposes that a decrease in the diameter of a fraction of the pores of the glomerular membrane impairs the filtration of larger molecules including cystatin C to a greater extent than smaller molecules such as water or creatinine." (PMID 40257600, 2025). "Similarly to UA, cystatin C concentrations might indicate the beginning of glomerulopathy, although they were within normal limits." (PMID 33143057, 2020). "The glomerular disease patients showed high levels of Scr, BUN, and cystatin C and low estimated glomerular filtration rate (eGFR) compared with controls." (PMID 35222740, 2022).
glomerulonephritis (5 papers, 2015 to 2022). A renal disorder characterized by damage in the glomeruli. "Development of glomerulonephritis was associated with a significant loss of renal function as demonstrated by a 6-fold increase in the plasma levels of cystatin-C at day 15 of disease in untreated and vehicle-treated groups, compared to normal controls." (PMID 26700873, 2015). "It has also been shown that U-FABP4 is increased before an increase in serum creatinine, clusterin or cystatin C in a drug-induced glomerulonephritis model with N-phenylanthranilic acid and puromycin in in vivo and in vitro studies." (PMID 33143633, 2020). "According to the cause of CKD, significant correlations were also observed between the RI, eGFR, and serum cystatin C in glomerulonephritis or nephrosclerosis group." (PMID 29513723, 2018). "In comparison, mice with glomerulonephritis which received BR-4628 showed a 30% reduction in plasma levels of cystatin-C at day 15, demonstrating that BR-4628 significantly improves renal function." (PMID 26700873, 2015). "Initial blood tests showed a near normal creatinine, but a raised cystatin C. Renal biopsy showed focal necrotizing glomerulonephritis with no acute tubular necrosis or chronic change." (PMID 35331328, 2022).